IFNG (interferon gamma)
Diseases named in the same sentence as IFNG in open-access papers (continued):
Sharing a sentence is not in itself a finding about the gene and the disease.
infection (continued). "To pre-empt development of infection, clinicians could give these patients prophylactic treatment, such as antibiotics, immunostimulant by interferon-gamma, or granulocyte-macrophage colony-stimulating factor, as used in septic shock." (PMID 21092108, 2010). "Similarly, different studies demonstrate that except for IL-12, infection with the highly virulent RH strain of T. gondii elicits elevated levels of pro-inflammatory cytokines, including IFNγ." (PMID 20865117, 2010). "This could in turn force the host to reprogram its own response to the infection, by silencing pro-inflammatory immune signaling pathways dependent on chemokines, IFNγ and TNF." (PMID 20824205, 2010). "However, the Th1 response characterized by the production of IFNγ peaked early at 15 days post-infection and decreased thereafter whereas IL-4 was expressed for longer (43 days post infection)." (PMID 20356390, 2010). "Transfer of Irga6 to the T. gondii PVM shortly after infection in IFNγ-induced cells is associated with GTP binding raising the possibility that activation of Irga6 results from the receipt of a cellular signal stimulated by infection." (PMID 20109161, 2010). "Likewise, Irgb10 is phosphorylated by RH-YFP, but in IFNγ-induced cells though very weakly above a significant level of intrinsic, infection-independent phosphorylation." (PMID 21203588, 2010). "Therefore, we performed experiments at earlier time points and observed that production of IL-12 and IFNγ was significantly impaired in the peritoneal cavity and peritoneal cavity/spleens from 3d mice at 3 and 5 days post-infection, respectively." (PMID 20865117, 2010). "In addition, maximal IFNγ release levels upon Ag85A stimulation post-infection correlate well and inversely with disease outcome by gross pathology scoring." (PMID 19367339, 2009). "To determine whether there was selective depletion of Th17 cells over other Th populations (e.g., those producing IFNγ, IL-4, or MIP1β) we measured the ratio between Th17 cells and these other populations as a function of time post-infection." (PMID 19214220, 2009). "Interferon gamma (Ifng) down regulates Kit ligand (Kitl) and Epor and may be an important contributor to anaemia of infection." (PMID 19365556, 2009). "Our results suggest a role of acidic pH in the control of intracellular Leishmania growth early during infection and identify for the first time an unexpected role of Stat1 in natural anti-microbial resistance independent from its function as IFNγ-induced signal transducer." (PMID 19381261, 2009). "Association between multiplicity of infection of HIV-1 (BaL) required for the 50% inhibitory effect of PBMC (Infectivity) and the proliferative response, percentage of IFNγ produced and CD25+FoxP3+ T cells (T regs) of CD4+ T cells; analysis by Mann Whitney test." (PMID 19956755, 2009). "Thus, the ANOVA tests detect the strongest effect of FIVC infection at days 37 and 59 and indicate IFNγ as a “driver” of the immune response to PLV infection at all time points." (PMID 19806226, 2009). "Therefore we checked the effect of IFNγ on the course of hMDMs infection with three different S. aureus strains." (PMID 18183290, 2008). "In addition, infection of immature human DC with L. infantum results in increased CD1d cell surface expression, and subsequent increased recognition and killing by IFNγ-producing iNKT cells." (PMID 18463695, 2008). "In our model, macrophages are activated with LPS and IFNγ prior to infection." (PMID 18769721, 2008). "Besides IFNγ stimulation, the infection of C57BL/6 mice with L. monocytogenes led to a rapid upregulation of all tested mGBPs in the liver." (PMID 18402675, 2008). "Bacterial clearance at three weeks post infection coincides with increases in circulating anti-Salmonella antibodies, increased T cell proliferation to Salmonella challenge and increased expression of interferon gamma." (PMID 16221297, 2005).
infection (continued). "In chronically S. haematobium‐infected adults with low intensities of infection, stimulation of PBMCs ex vivo with adult worm antigen (AWA) resulted in higher secretion of TGFβ and IL‐10 by female‐derived cells, but lower secretion of Th1‐associated TNF and IFNγ." (PMID 41546136, 2026). "Likewise, macrophage F4/80 expression decreases in response to IFNγ stimulation during infection." (PMID 39807873, 2025). "However, depending on the levels of type I IFNs, B cells may be inhibited along with reducing macrophage responses to IFNγ thereby facilitating infection." (PMID 40599652, 2025). "In line with previous findings in this infection model, a primary immune response against Mtb became evident from 3 to 4 weeks after the first challenge by showing increased frequencies of antigen-specific IFNγ-secreting peripheral blood mononuclear cells (PBMC)." (PMID 41120776, 2025). "Our findings demonstrate that infection of infiltrating monocytes with M. marinum alters their cytokine expression profile, induces glycolytic metabolism, hypoxia-mediated signaling, nitric oxide synthesis, tissue remodeling, and suppresses responsiveness to IFNγ." (PMID 39915532, 2025). "Interestingly, the stimulation of pancreatic islets with very high concentrations of TNF, IFNγ and IL-1β inhibited insulin secretion, indicating that during severe, life-threatening infection these cytokines are involved in facilitating stress-induced hyperglycemia." (PMID 39107476, 2024). "Thus, we tested whether recombinant human IFNγ (rIFNγ) influences Ser/5-HT effects on infection of U-87 MG cells by T. cruzi." (PMID 38776344, 2024). "However, the latent M. tuberculosis infection, in a subset of BCG-vaccinated infants that maintain a balanced immune response, can progress into an active infection, which, in turn, elevates the levels of IFNγ, inflammation, and immune activation, resulting in a type-1 skewed immune response." (PMID 38675778, 2024). "IFNγ is also contributed by NK cells and NK activation may play a critical role in viral uptake and killing, thus reducing the burden of viral load at the initial stages of infection." (PMID 38722827, 2024). "At 2 h post-infection, the bacterial load in the two cell types was similar, while at 72 h post-infection, the bacterial burden in IFNγ-expressing macrophages was significantly higher than that in the control cells, indicating intracellular IFNγ directly boost mycobacterial growth in macrophages." (PMID 39222120, 2024). "Interestingly, orotracheal infection also induced the expression of IFNγ in the trachea at 4 dpi." (PMID 39599832, 2024). "In addition, autoantibodies against IFNγ increase the risk of infection with nontuberculous mycobacteria and Mtb." (PMID 39309852, 2024). "Furthermore, the production of IFNγ is not necessarily a hallmark of all of the specialized subsets found to affect the outcomes of infection, as discussed here." (PMID 38607077, 2024). "Numerous studies have demonstrated that it takes at least 24 hours of IFNγ pre-treatment to affect chlamydial growth, so it is still unclear how down-modulation of these signaling components may help Chlamydia during primary infection." (PMID 39194253, 2024). "Therefore, IFNγ-treated HL1 cells were infected with 0.5 multiplicity of infection (MOI) CVB3." (PMID 39195892, 2024). "Other explanations could be different times of infection, amounts of IFNγ and/or MOIs." (PMID 36603017, 2023). "However, acute infection followed by sustained activation of innate immune response and IFNγ production could activate antigen-presenting cells as well." (PMID 36750846, 2023). "Also, some animals may have been in the early stages of infection when IFNγ responses could be dominant over antibody responses." (PMID 36726018, 2023).
infection (continued). "Interestingly, in contrast to polarisation of BMDM with IL-4 prior to infection, treatment of non-polarised S.tm-infected BMDM with IL-4 resulted in improved infection control whereas stimulation with IFNγ led to an increase in intracellular bacterial numbers compared to unstimulated controls." (PMID 37190073, 2023). "In vitro studies suggest that IFNγ fuels astrocyte infection by T. cruzi and implicate IFNγ-stimulated infected astrocytes as sources of TNF and nitric oxide, which may also contribute to parasite persistence in the brain tissue and promote behavioural and neurocognitive changes." (PMID 37018799, 2023). "Still, IFNγ (or any other simultaneously produced effector molecules) may play a dual role in the CNS, shutting down the high parasite burden in the acute infection, while fuelling low parasitism in the chronic phase of infection." (PMID 37018799, 2023). "Thus, IFNG is very likely to be both necessary for viral clearance, but also highly pro-inflammatory, so inhibitors of IFNG would only be a useful therapeutic after infection is resolved." (PMID 37361874, 2023). "Moreover, CS impairs the antiviral response of airway epithelial cells by inhibiting the production of interferon gamma (IFN-γ) and IFN-γ-dependent signalling, resulting in further increased susceptibility to infection-associated tissue damage which can, in turn, fuel COPD progression." (PMID 36839377, 2023). "Indeed, IFNγ was highly upregulated in maternal serum in response to Pru infection." (PMID 37259639, 2023). "Thus, the presence of IFNγ may promote the infection of astrocytes by both pathogens, a matter to be further mechanistically explored." (PMID 37018799, 2023). "The integration of an IFNγ-induced pathway with post-translational control of innate immune defense could cover a broad range of pathogens and enable cells to autonomously regulate immunity depending on their infection status." (PMID 37797010, 2023). "Interestingly, in our experiments, liver Ifng expression was significantly diminished 6 h post-infection in Hjv−/− mice, suggesting that perhaps tissue-resident Th1 or NK T cells could be an important source of IFNγ, which then enters the circulation." (PMID 36675185, 2023). "In some cases, the causative role of ACAAs in disease appears more straightforward (e.g., anti-IFNγ auto-antibodies in NTM infections), but in most infections, it remains unknown whether the ACAAs are indeed the cause or a result of the infection and how big their role exactly is." (PMID 38203686, 2023). "Hence, it plausible that with a less virulent infection, maternally‐derived IFNγ may be a more prominent driver of the HSC response, whereas with more virulent infections other cytokines, such as IL‐6 and IL‐1α, may further impact HSC function." (PMID 37259639, 2023). "Due to the acute infection caused by IAV in our study, we therefore speculated that the decreased CD4+ T cells in the co-infected group contributed to less IFNγ production, thereby leading to the diminished killing effects of CD8+ T cells against secondary T. gondii infections." (PMID 37235437, 2023). "In addition, through the interferon-gamma (IFN-γ) signaling, M. tuberculosis biases hematopoiesis towards the proliferation of the myeloid hematopoietic stem cells (HSCs) rather than lymphoid cells, which include monocytes to propagate infection." (PMID 38033005, 2023). "Since T. gondii disseminates to other organs and ILC1s are critical for IFNγ-dependent control of infection in the intestine, it would be interesting to test whether these cells undergo plasticity in the gut, or they migrate from other inflammatory sites to facilitate host protection." (PMID 36838426, 2023). "Besides IFNγ, GM-CSF is one of the major cytokines released by T cells orchestrating the crosstalk between adaptive and innate immune responses during inflammation and infection." (PMID 35983034, 2022).
infection (continued). "However, control over viremia failed to be maintained by a number of animals during the chronic phase of infection, despite the preservation of IFNγ-producing CD8+ T-cell levels, resulting in increased viral loads, the loss of CD4+ T cells, and rapid progression to AIDS." (PMID 36033843, 2022). "Untreated mice in both groups exhibited evidence of active infection at 14 days post-exposure and beyond and as expected, all mice in the IFNγ deficient group not receiving prophylaxis experienced uncontrolled infections and had to be euthanized by ~21 days post-exposure." (PMID 36315597, 2022). "The IL-10 responses generated by both CD8+ and CD4+ T cells were present within 1 month of infection in response to a mix of pp71 and US3 proteins, but not in response to latency associated proteins, despite IFNγ-specific responses being detected from early timepoints post infection." (PMID 36558866, 2022). "There may be opposing effects of M-CSF, LPS, and IFNγ in the M1 medium that can impact infection." (PMID 36228018, 2022). "However, IL-27 also promotes IL-10 production, (reviewed in a later section) which could downregulate IFNγ production later during infection to mediate immunopathology." (PMID 35634328, 2022). "To evaluate whether SLAMF8 can modulate the expression of TLR4 and SLAMF9 and, therefore, influence the observed phenotype in SLAMF8-deficient mice, we analyzed their expression in pMø by RT-PCR after treatment with IFNγ (100 U/ml for 16 h) and infection with S. typhimurium at different time points." (PMID 35837407, 2022). "They share characteristics of effectors generated during an acute infection, having lower levels of inhibitory receptors (for example, TIM-3) and transcription factors associated with T cell exhaustion (for example, Tox) and higher levels of IFNγ and IL-2 production." (PMID 36171284, 2022). "Because most PBMC samples from asymptomatic patients were collected <10 days after the first positive RT-PCR testing of SARS-CoV-2, we speculated that higher expression of IFNG in T cells plays an important role in antiviral infection, especially during the early stage of infection." (PMID 34531370, 2021). "Higher IL-2 responses following vaccination may be due to shorter exposure to vaccine antigen compared with persistent antigen after infection, and consequent enhanced development of uncommitted IL-2+IFNγ- memory CD4+ T-cells, although this remains to be tested." (PMID 34960185, 2021). "Therefore, we questioned whether the IFNγ-mediated effector function of the TH1 cells remained intact throughout the UgCl223 infection." (PMID 35186781, 2021). "Many recent studies have shown that the presence of LEVs released from L. (L.) donovani modify the IFNγ-induced production of pro- or anti-inflammatory cytokines by cultured human monocytes, favoring the Th1 immune response and the elimination of Leishmania, which leads to the control the infection." (PMID 34683402, 2021). "In TB disease, evidence also suggests that MAIT cells might be recruited to sites of infection and have been shown to be lost in blood of people with active TB but enriched in the lungs, with a capacity to secrete IFNγ in response to co-culture with M.tb-infected lung epithelial cells." (PMID 33828558, 2021). "By focusing on the two macrophage states detected 8 h after the infection, we found the first state to be characterized by the module containing Irf7, Hmga1, Zfp275, and Stat1 that has been previously shown to initiate the inflammatory response to pathogens in an interferon gamma dependent manner." (PMID 34404761, 2021). "In the site of infection, recruited monocytes differentiate into macrophages that show extensive plasticity, depending on converging signals delivered by the numerous factors (microbial products, cytokines (IFNγ, TNFα) and growth factors, present in the local tissue environment." (PMID 33898331, 2021).
infection (continued). "Indeed, within several hours following infection, macrophages are able to produce and release a large amount of pro-inflammatory and Th1-type cytokines, such as tumor necrosis factor α (TNFα), interferon gamma (IFNγ) and interleukin-12 (IL12)." (PMID 34946140, 2021). "As IFNγ-producing NK cells and ILC1s accumulate at mucosa at the same time post infection, it will be important to define whether these subsets play unique or redundant roles during infection." (PMID 34938670, 2021). "Likewise, upon immunization with Lm, CD8+ TM cells induced after VSV vaccination also induced a rapid and coordinated burst of Ag-dependent chemokines and Ag-independent IFNγ accumulation, peaking at ~16 hours after challenge infection, with 40 to 60% of chemokine/IFNγ+ OT-I TM cells." (PMID 34516896, 2021). "IFNγ is typically expressed as part of the type 1 immune response, and analysis of specific immune cell populations during Citrobacter rodentium infection of the murine colon has revealed that this pathogen induces a robust type 1 response that is important for clearing the infection." (PMID 33529199, 2021). "However, due to the known role of IFNγ in macrophage activation, we cannot exclude a potential role for IFNγ in iKIR-treated mice, as we only determined microbial clearance in a single time point after infection." (PMID 33690673, 2021). "Thus, to overcome the potential effect of IWR-1-endo on unrelated host cell functions and establish a direct link between infection and Wnt/β-catenin activation, we infected naïve or IFNγ-stimulated BMDMs with a mutant Toxoplasma strain (RHΔASP5) and quantified parasite burden using qPCR." (PMID 33014886, 2020). "Although Tem cells are less proliferative and could not persist for a long term, they are ready to provide immediate protection at infection sites via producing multiple cytotoxic molecules, including granzyme B (Gzmb), perforin, interferon gamma (IFNγ), tumor necrosis factor (TNF), etc.." (PMID 32983095, 2020). "Similarly to IL1β, IFNγ is also an important mediator of the immune response to infection but when chronically elevated may have important immunopathological consequences." (PMID 33182721, 2020). "Therefore, we hypothesized that IL-18 levels in the gut promoted early innate defenses to infection, while priming mucosal IFNγ to mediate pathogen clearance in the later stages." (PMID 32330185, 2020). "However, IL-17A may play more of a protective role as it seems to be upregulated in early infection but is downregulated in late clinical disease, similar to what is observed with IFNγ." (PMID 32258066, 2020). "Such “hypoferraemia of infection” is a host defence strategy to limit iron availability from invading pathogens, and involves sustained production of proinflammatory cytokines such as interferon-gamma (IFN-γ), tumour necrosis factor-alpha (TNF-α), interleukin (IL)-1 and IL-6." (PMID 32972031, 2020). "Finally, it was found that infection efficiencies of >50% could be achieved for M2 macrophages if the cells were IFNγ-stimulated 24 h prior to infection and then repolarized to M2." (PMID 32857777, 2020). "Furthermore, a higher reduction rate in the number of chlamydial IFUs was observed in the IFNγ pre-infection treatment (67.6% at 103 IU/mL and 71.2% at 102 IU/mL) rather than in the IFN-γ post-infection treatment (36.8% at 103 IU/mL and 14.8% at 102 IU/mL, p < 0.01)." (PMID 32050567, 2020). "Additionally, in a study showing that immunization intravenously could protect mice against subcutaneous infection, this protection was mediated by CD4+ T cells and was associated with an increase in IFNγ production." (PMID 33291260, 2020). "Finally, also IFNγ-/- C57BL/6 mice showed reduced survival in the infection with R. australis." (PMID 33091016, 2020).